IGF1 (insulin like growth factor 1)
Diseases named in the same sentence as IGF1 in open-access papers (continued):
Sharing a sentence is not in itself a finding about the gene and the disease.
osteoporosis (173 papers, 2008 to 2026). A condition of reduced bone mass, with decreased cortical thickness and a decrease in the number and size of the trabeculae of cancellous bone (but normal chemical composition), resulting in increased fracture incidence. "Protein-energy deficits reduce serum IGF-1, a critical anabolic factor for bone and muscle tissue, thereby accelerating osteoporosis and elevating fracture risk." (PMID 40869488, 2025). "Hormonal changes in diabetic patients, such as deficiencies in vitamin D, insulin-like growth factor-1, and testosterone, contribute to bone fragility and subsequent osteoporosis." (PMID 40134912, 2025). "Transfusions also help lower the risk of osteoporosis because blood transfusion increases secretion of insulin-like growth factor-1 (IGF-1) and IGF-binding protein-313,14." (PMID 40691682, 2025). "IGF-1 levels are useful tools for evaluating the risk of fractures in adults and children with osteoporosis." (PMID 38610974, 2024). "According to the UK dataset, IGF-1 levels were associated with a reduced risk of osteoporosis, as indicated by the weighted median method (Odds Ratio [OR] = 0.998, 95% CI = 0.997–1.000, P = 0.032)." (PMID 38260127, 2023). "IGF-1 level is associated with a reduced risk of osteoporosis, as indicated by the weighted median method (odds ratio [OR] = 0.998, 95% CI = 0.997-1.000, P = 0.032)." (PMID 38260127, 2023). "In our analysis using data from the UK trait, IGF-1 level is associated with a reduced risk of osteoporosis, as indicated by the weighted median method (OR=0.998, 95% CI = 0.997-1.000, P = 0.032)." (PMID 38260127, 2023). "This association mirrors the situation observed in men with idiopathic osteoporosis (IOM), who develop osteoporosis at a young age, further highlighting the potential pathogenic role of IGF-1 in the development of low bone mass." (PMID 38260127, 2023). "Decreased IGF1 signaling is however also associated with several age-related diseases such as osteoporosis, cardiovascular disease, skeletal muscle wasting and atrophy, as well as neurological ailments such as dementia." (PMID 37908640, 2023). "While decreased IGF1 levels have been associated with longevity in numerous model organisms, as well as in humans, decreased IGF1 expression with age has also been correlated with increased risk of osteoporosis, muscle-wasting, and dementia." (PMID 37908640, 2023). "A prospective study should be conducted to explore the causality between IGF-1 and osteoporosis in CD patients." (PMID 37441368, 2023). "Estrogen itself and its effect on increasing insulin like growth factor 1 (IGF1) and GH release, are important factors for bone maturation and so delayed puberty is a major risk factor for growth retardation, osteoporosis, and reduced final height." (PMID 35729519, 2022). "The cutoff values of IGF-1 for predicting osteoporosis, prevalent fracture and high fracture risk were 61.5 ng/mL (sensitivity/specificity, 0.545/0.894), 69.5 ng/mL (0.633/0.784) and 61.5 ng/mL (0.512/0.929), respectively." (PMID 36010307, 2022). "GCs cause osteoporosis by inhibiting Wnt signalling and also decrease IGF-1 transcription in osteoblasts." (PMID 35191394, 2022). "The present findings suggest that osteoporosis and osteoarthritis were associated with early LS, and a decrease of the serum IGF-1 level was also an independent factor related to early LS." (PMID 35948948, 2022). "This study aimed to evaluate the association of serum IGF-1 levels with osteoporosis, prevalent fractures and fracture risk based on the Fracture Risk Assessment Tool (FRAX) in patients with primary biliary cholangitis (PBC)." (PMID 36010307, 2022). "On multiple linear regression analysis, age, IGF-1, osteoporosis, and osteoarthritis were significantly associated with the Locomo-25 score." (PMID 35948948, 2022). "The level of GH and IGF1 decrease with aging, correlating with the increased risk of osteoporosis and fragility fracture in elderly population." (PMID 35665221, 2022).
osteoporosis (continued). "The present findings suggest that osteoporosis and osteoarthritis were associated with early LS, and a decrease of the serum IGF-1 level was a significant independent factor for early LS." (PMID 35948948, 2022). "The cutoff values of serum IGF-1 for predicting osteoporosis, prevalent fracture and high fracture risk were 61.5, 69.5 and 61.5 ng/mL, respectively." (PMID 36010307, 2022). "In end-stage liver disease, hepatocellular dysfunction and reduced GH receptors lead to low serum IGF-1 levels, subsequently causing osteoporosis." (PMID 33807573, 2021). "25(OH)D concentration showed a negative correlation with BALP and a positive correlation with IGF-1, indicating the decline of osteoblast, risk of osteoporosis." (PMID 35223754, 2021). "Osteoporosis in cholestatic liver disease is associated with impaired bone formation, increased bilirubin and sclerostin, and lower insulin-like growth factor-1." (PMID 33807573, 2021). "Our findings showed a strong significant association between Cd levels and IGF-1 in osteoporosis subjects." (PMID 32629669, 2020). "Using stepwise linear regression analysis, only Cd was identified to be significantly associated with IGF1 in osteoporosis, explaining 3% (confidence interval 0.01–0.05; P = 0001) of the variance perceived." (PMID 32629669, 2020). "Stratified according to the presence of osteoporosis, almost all minerals were associated with IGF1 with the exception of Ni." (PMID 32629669, 2020). "Stratified according to the presence of osteoporosis, only Cd was associated with IGF-1 in the osteoporosis group." (PMID 32629669, 2020). "Aging also causes a disturbance of other hormones, including thyroid hormones, insulin-like growth factor-1 and parathyroid hormones, as well as transient low-grade inflammation which predispose an individual to osteoporosis." (PMID 31936034, 2020). "In the osteoporosis group, IGF-1 was significantly associated with Mn, Ni, and Cd and was inversely associated with T-Score." (PMID 32629669, 2020). "The Framingham Osteoporosis Study, carried out in men and women aged 72–74, reported that high IGF1 levels are associated with greater BMD in older women." (PMID 31581477, 2019). "Numerous studies have shown that the occurrence and development of cardiovascular diseases, malignant tumors, osteoporosis, and other diseases are associated with circulating IGF-1 levels." (PMID 31077177, 2019). "The summarized OR suggested that there existed a statistically significant association between rs35767 in IGF-1 gene and the osteoporosis predisposition (OR 1.21, 95% CI 1.07, 1.37; P = 0.002)." (PMID 29747606, 2018). "There have been a series of studies looking into the association between the rs35767 polymorphism in IGF-1 gene and osteoporosis predisposition, while these results acquired were conflicting and as yet no robust evidence was available on this association." (PMID 29747606, 2018). "The present systematic review and meta-analysis was performed to appraise and synthesize the existing evidence, so as to provide a more precise and reliable association between polymorphisms in IGF-1 gene and osteoporosis." (PMID 29747606, 2018). "Several studies looking into the association between insulin-like growth factor-1 (IGF-1) gene polymorphisms and osteoporosis predisposition have been conducted among Chinese population with conflicting outcomes." (PMID 29747606, 2018). "The single nucleotide polymorphisms (SNPs) located in IGF-1 gene also had been identified to be significantly associated with osteoporosis by Li and coworkers." (PMID 29747606, 2018). "Aging is associated with a decrease in GH secretion and serum IGF-1 concentration has been reported to be significantly lower in men and women with osteoporosis." (PMID 25147565, 2014). "We observed the relationship between polymorphisms of IGF-1(rs35767, rs2288377 and rs5742612) with osteoporosis and BMD in the postmenopausal female population in our study." (PMID 24639846, 2014).
osteoporosis (continued). "In humans, reductions in IGF-1 also associate with higher incidence of diabetes, osteoporosis, dementia, and Alzheimer disease." (PMID 24341939, 2014). "The relationship between circulating IGF-1 levels and disease risk among women is complex as studies have shown that IGF-1 can be either positively (e.g. cancer) or negatively (i.e. osteoporosis, heart disease) associated with adverse health outcomes." (PMID 21599947, 2011). "Two factorsthat impact bone formation are the accumulation of advanced glycation end productsin collagen and oxidative stress resulting from elevated blood glucose levels.Furthermore, the occurrence of osteoporosis has been associated with reduced levelsof insulin and insulin-like growth factor-1." (PMID 41259452, 2025). "Moreover, blood transfusion plays a critical role in decreasing the risk of osteoporosis in thalassemic patients by increasing the insulin-like growth factor-1 (IGF) and IGF-binding protein-3 (BP) secretion." (PMID 37174943, 2023). "Another study found that a bioactive compound, icariin, which could be isolated from Epimedium koreanum (Chaoxianyin Yang Huo), ameliorated estrogen deficiency-induced osteoporosis by promoting insulin-like growth factor 1 (IGF-I) signaling in bone." (PMID 37940992, 2023). "Thus, we considered there is only some mild difference between the two traits, which indicates the causal effects of IGF-1 in reducing the prevalence of osteoporosis held population or ethic specificity." (PMID 38260127, 2023). "Another parameter often used in the estimation of osteoporosis risk is IGF-1." (PMID 37960234, 2023). "On the other hand, it has been reported that there is a relationship between the IGF-1 level and BMD, but it is unclear whether low levels of IGF-1 cause osteoporosis." (PMID 35948948, 2022). "Mechanisms such as decreased vitamin D and insulin-like growth factor-I (IGF-1), increased inflammatory mediators and fibronectin isoforms can further affect osteoblast and osteoclast function, leading to osteoporosis and an increased risk of fragility fractures." (PMID 36404305, 2022). "IGF1 also played a vital anabolic role in skeletal development, and low expression of IGF1 could induce risk of osteoporosis fracture, which was consistent with the conclusion in this study." (PMID 35479581, 2022). "Low IGF-1 levels could be another factor that could be implicated in TM-associated osteoporosis development." (PMID 35243531, 2022). "We hypothesised that low IGF-1 and high sclerostin might act as markers for decreased bone formation in diabetic patients as they are associated with a higher risk of osteoporosis and fractures." (PMID 34690653, 2021). "Lower concentrations or circulating IGF-1 have been associated with osteoporosis." (PMID 32919376, 2020). "It is considered essential for longitudinal bone growth, skeletal maturation, and bone mass acquisition during growth performance and maintenance, whereas lower serum IGF-1 levels are associated with the prevalence of fractures and increased risk of osteoporosis in postmenopausal women." (PMID 32962034, 2020). "A number of factors are responsible for osteoporosis, including alteration in the metabolism of vitamin D and calcium, vitamin K deficiency, hormonal dysregulation, release of cytokines and deficiency of insulin-like growth factor 1 (IGF-1)." (PMID 33083184, 2020). "IGF-1 may be used as biomarker for the early detection of osteoporosis caused by Cd exposure and should be taken into consideration in investigations of such population." (PMID 32629669, 2020). "The anabolic effect of IGF-1 was mainly exerted on cortical and trabecular bone, and it is also of great importance for the achievement of the peak bone mass, which is a critical contributing factor for future risk of osteoporosis." (PMID 29747606, 2018).
osteoporosis (continued). "Considering the emergence of novel evidence on the association of IGF-1 polymorphisms and risk of osteoporosis, we set out to perform the present systematic review and meta-analysis to obtain a more credible association between IGF-1 polymorphisms and osteoporosis predisposition." (PMID 29747606, 2018). "Although the present meta-analysis has provided a more comprehensive evaluation and precise evidence of the currently available data on the association between the IGF-1 gene polymorphism and osteoporosis, there are still several limitations that should be pointed out." (PMID 29747606, 2018). "In addition, as with other complex disorders, osteoporosis risk was modulated by multiple genetic factors with synergetic effect other than IGF-1 gene." (PMID 29747606, 2018). "In humans, the physiological decline in GH and IGF-1 levels is linked to osteoporosis." (PMID 24341939, 2014). "Elevated IGF-1 levels may be associated with protection against age-related cognitive decline, cardiovascular disease and osteoporosis." (PMID 21693050, 2011). "CRD with airflow obstruction has been shown to represent a causative risk for osteoporosis, so elevation of IGF-1 levels may be particularly useful for elderly individuals with CRD." (PMID 19527531, 2009). "Moreover, we also found that those women with T alleles would have significantly lower BMD compared with those with C alleles, and thus IGF-1 polymorphism may be a potential indicator for osteoporosis in postmenopausal women." (PMID 24639846, 2014). "Lower IGF-1 levels among current users may also potentially lead to decreased bone mineral density, particularly in young women, while the higher levels we observed in older past users may decrease osteoporosis risk, reflecting observed relationships between IGF-1, bone density and osteoporosis." (PMID 21599947, 2011). "Emerging evidence highlights probiotics as potent modulators of IGF-1 bioactivity, offering therapeutic potential for osteoporosis." (PMID 40667443, 2025). "Reduced IGF-1 levels, as seen in liver diseases like non-alcoholic fatty liver disease, contribute to osteoporosis." (PMID 40430063, 2025). "Arginine stimulates insulin and IGF-1 secretion, both known as protective factors against osteoporosis, through promoting osteoblast proliferation and collagen synthesis." (PMID 40385578, 2025). "In type 1 diabetes, impaired bone formation is a result of absolute deficiency of insulin and insulin-like growth factor-1 (IGF-1), which leads to the risk of osteoporosis being 6 times higher than that of the general population." (PMID 39817378, 2025). "For instance, an IGF-1–gelatin sponge complex was locally applied in a rat model of osteoporosis, resulting in enhanced osseointegration and increased bone tissue formation around implants." (PMID 39859058, 2025). "The local delivery of IGF-1 accelerated bone formation in a rat fracture healing model, and IGF-1 administration in patients increased bone healing, with rapid clinical improvements in hip or tibial fractures during osteoporosis." (PMID 39682583, 2024). "It is well known that bone mineral density is the main indicator of osteoporosis, and IGF-1 is the main regulatory factor in the process of bone remodeling." (PMID 38840246, 2024). "Hormones such as testosterone, estrogen, growth hormone, insulin-like growth factor 1 (IGF-1), vitamin D, and cytokines fluctuate similarly in populations with osteoporosis and frailty." (PMID 38982542, 2024). "Reduced IGF1 has been linked to the development of age-related diseases such as osteoporosis, but female MYC haploinsufficient mice had a decreased incidence of osteoporosis, consistent with the finding that, in bone, IGF1 levels were unaltered." (PMID 38510176, 2024). "Our findings are consistent with the results of previous studies that found relationships between low IGF-1 levels, osteoporosis, and osteopenia." (PMID 38610974, 2024).
osteoporosis (continued). "Higher IGF-1 levels were associated with a lower risk of low BMD, suggesting its potential as a valuable tool for assessing osteoporosis in survivors of childhood acute leukemia." (PMID 38610974, 2024). "In patients with T2DM, the levels of IGF-1 may be influenced by insulin resistance and hyperglycemia, leading to a diminished anabolic effect on bone, which could potentially be one of the mechanisms underlying the increased prevalence of osteoporosis in these individuals." (PMID 39398331, 2024). "Our own research uncovers a positive association between IGF-1 SDS and BMD in patients with T2DM, underscoring the importance of regular monitoring of IGF-1 levels for early osteoporosis detection in this demographic." (PMID 39398331, 2024). "Our findings indicate that genetically proxied higher serum levels of IGF-1, IGFBP-3, IGF-LR1, and CTGF, as well as lower levels of CYR61, are associated with a decreased risk of osteoporosis." (PMID 38260127, 2023). "The development of thalassemia-associated osteoporosis (TAO) is mainly influenced by bone marrow expansion, hypogonadism, imbalanced cytokine profiles, and a defective growth hormone-insulin-like growth factor-1 (GH-IGF-1) axis." (PMID 37251676, 2023). "The decrease of serum IGF-1 protein has a significant relationship with osteoporosis, and strongly affects the incidence of osteoporotic fractures in postmenopausal women." (PMID 36602528, 2023). "Specifically, our findings indicate that lower levels of IGF-1, IGFBP-3, IGF-LR1, and CTGF, along with higher levels of CYR61, genetically contribute to an increased risk of osteoporosis." (PMID 38260127, 2023). "They found that the level of serum IGF-1 in females with osteoporosis was 30% lower than healthy females." (PMID 36967758, 2023). "The search string used for the literature search was “(insulin OR “insulin receptor” OR “insulin-like growth factor-1” OR IGF-1) AND (Wnt OR beta-catenin) AND (bone OR osteoporosis OR fracture OR osteoblast OR osteoclast OR osteocyte)”." (PMID 37569816, 2023). "However, our study indicated that a lower IGF-1 index level was significantly associated with low bone mass in young CD patients, which might provide a new aspect to understand the possible risk factors and mechanism of osteoporosis in CD patients." (PMID 37441368, 2023). "Age (β = 0.323, p < 0.001), IGF-1 (β = − 0.219, p = 0.011), osteoporosis (β = 0.273, p = 0.002), and osteoarthritis (β = 0.339, p < 0.001) were significantly associated with the Locomo-25 score." (PMID 35948948, 2022). "The pros and cons and timing of therapeutic intervention should be established by certain indicators, such as the FRAX and serum IGF-1 level, to rationally prevent the development of osteoporosis and fracture in patients with PBC." (PMID 36010307, 2022). "The prevalence of bone disorders (osteoporosis and prevalent fracture) and the 10-year FRAX-derived probability of MOF and HF (including high fracture risk) increased with decreasing serum IGF-1 levels." (PMID 36010307, 2022). "Other endocrine factors that can contribute to steroid-induced osteoporosis include suppression of insulin-like growth factor 1 (IGF1), and collagen degradation." (PMID 35275196, 2022). "The logistic regression analysis showed that participants with IGF-1 had an OR of 1.019 (95% confidence interval [CI] 1.002–1.039; p = 0.027) for LS adjusted by osteoporosis, osteoarthritis, and the propensity score estimated from sex, age, and BMI." (PMID 35948948, 2022). "After applying DGS, we found that five gene locus polymorphisms in the Asian population were associated with osteoporosis: VDR FokI (rs2228570), IGF1 (rs2288377), IGF1 (rs35767), TGF β1 T869C (rs1800470), and ESR2 RsaI (rs1256049)." (PMID 35452412, 2022). "The participants with decreased IGF-1 level had a significant OR for LS adjusted by osteoporosis, osteoarthritis, and propensity score estimated from sex, age, and BMI." (PMID 35948948, 2022).